CCAT2 (colon cancer associated transcript 2)
Diseases named in the same sentence as CCAT2 in open-access papers (continued):
Sharing a sentence is not in itself a finding about the gene and the disease.
ovarian carcinoma (continued). "Our results suggest a novel anti-cancer mechanism of vitamin D by targeting CCAT2 in ovarian cancer." (PMID 32230936, 2020). "The data suggest that calcitriol inhibits the migration of ovarian cancer cells mainly through suppressing the function of CCAT2." (PMID 32230936, 2020). "Another study has shown CCAT2 up-regulation in ovarian cancer samples compared with normal ovarian tissues and suggested a possible association with tumor progression and development." (PMID 28480695, 2017). "Levels of CCAT2 gene expression are higher in tissues and cell lines of ovarian cancer than in corresponding normal tissues." (PMID 28637507, 2017). "Knockdown of the lncRNA CCAT2 inhibited cell proliferation, migration and invasion, further highlighting the role of CCAT2 in cell biology and oncogenesis of ovarian cancer cells." (PMID 27283598, 2016). "This study assessed CCAT2 expression levels in ovarian cancer tissues, normal ovarian tissues and cell lines, by quantitative real-time PCR (qRT-PCR)." (PMID 27283598, 2016). "Using qRT-PCR, CCAT2 gene expression was assessed in 109 ovarian cancer tissue samples, 45 normal ovarian tissue specimens, and cultured ovarian cancer- or normal cells." (PMID 27283598, 2016). "In summary, this is the first report showing that lncRNA CCAT2 expression is significantly high in ovarian cancer tissues and cell lines." (PMID 27283598, 2016). "In order to explore the functional role of CCAT2 in ovarian cancer tumorigenesis, SKOV3 cells were transfected with si-CCAT2 or si-NC." (PMID 27283598, 2016). "Taken together, these findings demonstrated for the first time the clinical significance of the lncRNA CCAT2 in ovarian cancer." (PMID 27283598, 2016). "The lncRNA CCAT2 is a novel factor involved in ovarian cancer progression, and constitutes a potential prognostic biomarker and therapeutic target for patients with ovarian cancer." (PMID 27283598, 2016). "Starkly increased CCAT2 gene expression levels were found in ovarian cancer tissue samples compared with normal ovarian tissue specimens (P < 0.01)." (PMID 27283598, 2016). "However, CCAT2 expression in ovarian cancer and the underlying mechanism remain unknown." (PMID 27283598, 2016). "Expression levels of the lncRNA CCAT2 in ovarian cancer tissues and cell lines were significantly higher compared with values obtained for adjacent non-tumor tissues and normal ovarian epithelial cells." (PMID 27283598, 2016). "Expression levels of the lncRNA CCAT2 in ovarian cancer tissues, adjacent normal tissues, and cell lines were assessed by quantitative real-time PCR." (PMID 27283598, 2016). "In the present study, CCAT2 gene expression levels were significantly higher in ovarian cancer tissue samples and cell lines." (PMID 27283598, 2016). "Similarly, CCAT2, which is enriched in ovarian cancer tissues and cells, promotes proliferation by sponging miR-424-5p." (PMID 37190145, 2023). "Interestingly, treatment with calcitriol (vitamin D) on ovarian cancer cell lines had the same inhibitory effect that was achieved by silencing CCAT2." (PMID 34830370, 2021). "Our results show that calcitriol decreases lncRNA CCAT2 expression in ovarian cancer cells." (PMID 32230936, 2020). "Here, we foundd that calcitriol inhibited CCAT2 expression in ovarian cancer cell lines." (PMID 32230936, 2020). "Given the negatively regulatory effect of calcitriol on CCAT2, we studied whether calcitriol also inhibits the expression of c-Myc protein in ovarian cancer cells." (PMID 32230936, 2020). "Our findings suggest CCAT2 as a potential target for metastasis prevention in ovarian cancer." (PMID 32230936, 2020). "In addition, in the event of CCAT2 silencing in ovarian cancer cells, cell proliferation, migration and invasion are significantly suppressed." (PMID 28637507, 2017). "Moreover, CCAT2 knockdown in ovarian cancer cells markedly suppressed cell proliferation, migration, and invasion." (PMID 27283598, 2016).
ovarian carcinoma (continued). "Moreover, multivariate Cox analysis indicated that high CCAT2 expression was an independent predictor of ovarian cancer." (PMID 27283598, 2016). "In addition, CCAT2 was significantly up-regulated in four ovarian cancer cell lines (SKOV3, IGROV1, A2780, and OVCAR3) compared with normal human ovarian surface epithelial HOSE 6.3 cells (P < 0.01)." (PMID 27283598, 2016). "Finally, CCAT2 effects on ovarian cancer cell proliferation, migration and invasion were further determined via suppression of the lncRNA CCAT2 in vitro." (PMID 27283598, 2016). "Thus, further experiments are needed to identify the biological processes regulated by CCAT2 in ovarian cancer." (PMID 27283598, 2016). "Moreover, CCAT2 silencing in ovarian cancer cells markedly suppressed cell proliferation, migration, and invasion." (PMID 27283598, 2016). "Taken together, these findings suggest a potentially important role for CCAT2, which could serve as a potential biomarker and therapeutic target in ovarian cancer." (PMID 27283598, 2016). "Similarly, CCAT2 expression was upregulated in tissues and cell lines of ovarian cancer." (PMID 34204094, 2021). "As shown in the model, calcitriol suppresses ovarian cancer cell growth, migration and invasion by down-regulating CCAT2 and repressing its interaction with TCF4, decreasing CCAT2/TCF4 binding to the MYC promoter." (PMID 32230936, 2020). "However, CCAT2 expression and prognostic role in ovarian cancer remain unclear." (PMID 27283598, 2016). "Univariate Cox proportional hazards regression model analysis showed that relative CCAT2 expression level, distant metastasis, tumor grade, and FIGO stage were correlated with overall survival rate in ovarian cancer patients (P < 0.05)." (PMID 27283598, 2016). "Among 1680 patients with ovarian cancers, about 185 cases (11%) have the alterations in CCAT2 and 588 cases (35%) have the alterations in MYC, indicating a high incidence of the aberrant expression of CCAT2 and MYC in ovarian epithelial carcinomas." (PMID 32230936, 2020).
prostate carcinoma (14 papers, 2015 to 2024). A carcinoma that arises from epithelial cells of the prostate gland. "The SNP rs6983267 within lncRNA CCAT2 has been implicated in predisposition to colorectal and prostate cancer." (PMID 26430965, 2015). "In addition, different variants of CDKN2B-AS1 are associated with prostate cancer, and CCAT2 expression is upregulated in prostate cancer patients and affects prostate cancer development by altering the epithelial-mesenchymal transition." (PMID 36530425, 2022). "In this study, we investigated the effect of NaBu on the expressions of FOXCUT, HULC, and CCAT2 lncRNAs in two prostate cancers; PC-3 and LNCAP cell lines." (PMID 35178357, 2021). "VIRMA knockdown could decrease the m6A levels and stability of CCAT1 and CCAT2 lncRNA in prostate cancer." (PMID 33731118, 2021). "In this study, the transcriptional expression levels of three lncRNAs namely colon cancer associated transcript 2 (CCAT2), HULC, and FOXCUT, and the effect of NaBu on cell cycle control, apoptosis, and expressions of these lncRNAs were evaluated in two prostate cancer cell lines, PC-3 and LNCAP." (PMID 35178357, 2021). "Several other genes and ncRNAs at 8q24, such as POU5F1B (previously thought to be a pseudogene), PRNCR1, CASC11 and CCAT2, have also been shown to be overexpressed in prostate cancer and may also play a role in the development or progression of prostate cancer." (PMID 33374332, 2020). "Another study demonstrated that knockdown of VIRMA could decrease the stability of CCAT1 and CCAT2 lncRNA in an m6A-dependent manner to regulate MYC transcription, promoting progression of prostate cancer." (PMID 33731118, 2021).
hepatocellular carcinoma (9 papers, 2017 to 2023). A malignant tumor that arises from hepatocytes. "High CCAT2 expression is an independent risk factor of predicting shorter survival of hepatocellular carcinoma (HCC) patients." (PMID 35115025, 2022). "In HCC, Long non-coding RNA CCAT2 functions as an oncogene in hepatocellular carcinoma, regulating cellular proliferation, migration and apoptosis." (PMID 29050269, 2017). "However, it is still unknown whether CCAT2 is involved in autophagy and metastasis of hepatocellular carcinoma (HCC)." (PMID 34409736, 2021). "In hepatocellular carcinoma (HCC) cell models, CCAT2 was reported to promote cellular migration, proliferation, and decreased apoptosis by interaction with another member of the FOX gene family, FOXM1." (PMID 34830370, 2021).
non-small cell lung carcinoma (7 papers, 2016 to 2024). A group of at least three distinct histological types of lung cancer, including non-small cell squamous cell carcinoma, adenocarcinoma, and large cell carcinoma. "In another study, colon cancer-associated transcript 2 (CCAT2) was reported to promote invasion of non-small cell lung cancer, and had the potential as a biomarker for lymph node metastasis." (PMID 27999202, 2017). "CCAT2 promoted the occurrence of non small-cell lung cancer (NSCLC) by regulating the Wnt/β-catenin signaling pathway." (PMID 35115025, 2022). "A lot of lncRNAs, including MALAT1, HOTAIR, CCAT2, and AK126698, were found to be associated with non-small cell lung cancer (NSCLC) progression, metastasis, and invasion." (PMID 32607061, 2020). "Besides, CCAT2 promotes invasion of non-small cell lung cancer." (PMID 27015551, 2016).
bladder cancer (6 papers, 2016 to 2022). "For example, it is reported that lncRNA PVT1, SUMO1P3 and CCAT2 can facilitate cell proliferation as well as repress cell apoptosis in bladder cancer." (PMID 33855047, 2021). "For example, lncRNAs MALAT1, SUMO1P3, and CCAT2 have been reported to promote cell proliferation and suppress cell apoptosis in bladder cancer." (PMID 33537343, 2020). "Overexpression of CCAT2 was positively correlated with histological grade of bladder cancer (P = 0.014) and TNM stage (P = 0.016)." (PMID 27015551, 2016). "The relative expression level of CCAT2 was detected by performing real-time qPCR in a total of 48 bladder cancer tissues." (PMID 27015551, 2016). "The synthetic “tetracycline-on” switch, was used to regulate expression of double shRNAs targeting CCAT2 in response to different contentrations of doxycycline and to suppress progression of bladder cancer cells." (PMID 27015551, 2016). "In this study, we reported the construction of tet-inducible system of CCAT2 and detected its anti-cancer effects in bladder cancer." (PMID 27015551, 2016). "CCK-8 assay results suggested that si-CCAT2 significantly decreased cell proliferation in bladder cancer cells (p < 0.001 in two cell lines)." (PMID 27015551, 2016). "In this study, our data showed that CCAT2 was overexpressed in bladder cancer tissues and cell lines, and promoted progression of bladder cancer cells." (PMID 27015551, 2016). "The expression of CCAT2 can be quantitatively controlled by the synthetic “tetracycline-on” switch system in bladder cancer in response to different concentrations of doxycycline to inhibit the development of bladder cancer cells." (PMID 27015551, 2016). "Compared with the negative control, cell migration ability was obviously suppressed in bladder cancer cells transfected with tetracycline-inducible CCAT2 shRNA group (P<0.05 in T24 and P<0.01 in 5637)." (PMID 27015551, 2016). "In this study, data showed that the expression of non-coding RNA CCAT2 was upregulated in bladder cancer tissues and cell lines." (PMID 27015551, 2016). "High expression of CCAT2 was also positively associated with TMN stage and histological grade of bladder cancer." (PMID 27015551, 2016). "To further study the biological behaviors of CCAT2 in bladder cancer, we employed the CCK8, EdU assays, cell migration assay and cell apoptosis assays to detect cell growth, migration and apoptosis in bladder cancer cells through knock down of CCAT2." (PMID 27015551, 2016). "After silencing CCAT2, cell growth and cell migration were inhibited and cell apoptosis was increased in bladder cancer cells." (PMID 27015551, 2016). "Our data showed that the tet-inducible system could control two identical shRNAs targeting CCAT2 in a dosage-dependent manner and effectively inhibited the development of bladder cancer cells." (PMID 27015551, 2016). "It is the first study to investigate the functions of CCAT2 in bladder cancer." (PMID 27015551, 2016). "The data suggested that CCAT2 inhibited cell apoptosis of bladder cancer cells." (PMID 27015551, 2016). "At last, CCAT2 may become a novel molecular target for bladder cancer treatment and this device may be widely used in the cancer therapy in the future." (PMID 27015551, 2016). "Here, we found that CCAT2 was upregulated in bladder cancer tissues and cell lines." (PMID 27015551, 2016). "In summary, our data indicated that CCAT2 may be an oncogene and a therapeutic target in bladder cancer." (PMID 27015551, 2016). "Further experimental results revealed that knockdown of CCAT2 could decrease cell proliferation and migration as well as induce apoptosis in bladder cancer cells." (PMID 27015551, 2016). "However, the role of CCAT2 in the development of bladder cancer is unclear and is needed to be studied." (PMID 27015551, 2016). "In conclusion, CCAT2 promotes progression of bladder cancer cells." (PMID 27015551, 2016). "However, the relationship between CCAT2 and bladder cancer is unclear." (PMID 27015551, 2016).
bladder cancer (continued). "Through the statistical analyses, we also found that the high expression level of CCAT2 was positively correlated with histological grade and TNM stage of bladder cancer." (PMID 27015551, 2016). "Bladder cancer cells were maintained in 6-well plates and transfected with plasmids expressing either the corresponding tetracycline-inducible CCAT2 shRNA or the negative control." (PMID 27015551, 2016). "The results showed that, compared with the negative control, tetracycline-inducible CCAT2 shRNA significantly suppressed proliferation when added with 2 ug/ml doxycycline in bladder cancer T24 and 5637 cells (P < 0.001 in two cell lines)." (PMID 27015551, 2016).
breast tumors (6 papers, 2013 to 2023). "Patients whose primary breast tumors showed a high expression of NEAT1, colon cancer associated transcript 2 (CCAT2), or metastasis associated lung adenocarcinoma transcript 1 (MALAT1) had shorter overall survival (OS)." (PMID 30545127, 2018). "Correspondingly to our observation in cultured cell lines (6 out of 40, 15%), levels of CCAT2 were undetectable within 35 amplification rounds in 238 out of 997 (24%) of the primary breast tumors from the EMC patient set." (PMID 24077681, 2013). "Long non-coding RNA CCAT2 promoted breast tumor growth by regulating the Wnt signaling pathway." (PMID 29113337, 2017). "In addition, previous findings demonstrated that CCAT2 is upregulated in breast tumors; indeed, CCAT2 silencing decreases cell proliferation and invasion in vitro through the Wnt/β-catenin signaling pathway." (PMID 27283598, 2016). "Therefore, additional larger studies are needed to assess the levels of CCAT2 in breast tumors versus normal tissues in multiple patient populations." (PMID 24077681, 2013). "The inverse correlations observed between transcript levels of both studied genes in the present study and disease stage are in accordance with the parallel expression of CCAT2 and MYC expressions in breast tumors, which has been observed in a previous study." (PMID 28480695, 2017).
esophageal cancer (6 papers, 2017 to 2024). A primary or metastatic malignant neoplasm involving the esophagus. "In the context of esophageal carcinoma, CCAT2 also serves as an oncogene, which promotes radiotherapy resistance." (PMID 34386421, 2021). "lncRNA CCAT2 was up-regulated in esophageal cancer tissues and positively correlated with TNM stage and lymph node metastasis." (PMID 28388588, 2017). "This study this presents CCAT2 as a new therapeutic target for the treatment of esophageal cancer." (PMID 34386421, 2021). "Patients with high CCAT2 expression and MYC amplification had an increased risk of cancer-related death, supporting that CCAT2 is a predictive biomarker and therapeutic target for esophageal cancer." (PMID 28388588, 2017). "Treatment of esophageal cancer cells with a Wnt inhibitor (FH535) recapitulated the effects of CCAT2 inhibition, indicating that CCAT2 exerts cancer-promoting effects through the Wnt/β-catenin pathway." (PMID 35241975, 2022). "This demonstrates that UCA1, POU3F3, CCAT2, HOTAIR, and uc002yug. could be important prognostic factors among patients with esophageal cancer." (PMID 35241975, 2022).
esophageal squamous cell carcinoma (6 papers, 2016 to 2022). Esophageal squamous cell carcinoma (ESCC) is a type of esophageal carcinoma (EC) that can affect any part of the esophagus, but is usually located in the upper or middle third. "CCAT2, a long non-coding RNA, promoted the invasion and tumorigenic potential of esophageal squamous cell carcinoma (ESCC) by decreasing the expression of miR-200b." (PMID 35682560, 2022). "In esophageal squamous cell carcinoma (ESCC), LncRNA CCAT2 increases IGF2BP2 expression, and then IGF2BP2 improves mRNA stability of thymidine kinase 1 (TK1) in m6A modification manner, which promotes tumor progression." (PMID 35541906, 2022).
lymph node metastasis (5 papers, 2016 to 2022). "In the multivariate analysis, lymph node metastasis (HR = 0.553, 95%CI: 1.684–14.690, P = 0.004) were independent factors associated with OS, but the influence of CCAT2 (HR = 0.654, 95%CI: 0.737–9.575, P = 0.135) on OS was lost." (PMID 35115025, 2022). "In the univariate analysis, FIGO stage (P = 0.021), lymph node metastasis (P = 0.001) and CCAT2 (P = 0.032) were associated with OS." (PMID 35115025, 2022). "Univariable analysis showed that FIGO stage, Lymph node metastasis and CCAT2 were all significantly associated with OS." (PMID 35115025, 2022). "Moreover, abnormal expression of CCAT2 was suggested to be associated with lymph node metastasis,distant metastasis and overall survival." (PMID 29088900, 2017). "The lung AC-specific lncRNA colon cancer-associated transcript 2 (CCAT2) displays altered expression, promotes invasion of NSCLC and can serve as a biomarker for lymph node metastasis." (PMID 28035947, 2016). "CCAT2 relative expression was positively correlated with tumor Federation of Gynecology and Obstetrics (FIGO) stage, SCC-Ag and lymph node metastasis (LNM) (all P < 0.05)." (PMID 35115025, 2022). "Furthermore, we measured CCAT2 levels in CRC with and without lymph node metastasis and found that CCAT2 was upregulated in the former case but not the latter." (PMID 34868956, 2021).